CXCL10 (C-X-C motif chemokine ligand 10)
Diseases named in the same sentence as CXCL10 in open-access papers (continued):
Sharing a sentence is not in itself a finding about the gene and the disease.
tumor (continued). "Further studies to evaluate the different threshold levels of CXCL10 between tumor and immune cells to activate the CXCR3/pSrc pathway or to deliver tumor-selective CXCL10 inhibitors or CXCR3 inhibition will be considered." (PMID 36612121, 2022). "Our results indicated that the RORγt agonist promoted CD8+ T cell tumor infiltration by increasing MoDCs, which secrete CXCL10 in the TME." (PMID 35459193, 2022). "Serum CXCL10 levels in patients at late tumor stage showed significant differences compared with the levels observed in patients at early tumor stage (P < 0.01)." (PMID 36207693, 2022). "We identified SPATA2 and its interacting partner, CYLD, as tumor-intrinsic regulators of T cell chemokines, including CXCL10, via a novel mechanism." (PMID 36531014, 2022). "Although IFN-γ induced CXCL10 is secreted by various cell types, the major source of CXCL10 at the tumor site is CD11b+ myeloid cells." (PMID 35459193, 2022). "Previous studies have revealed that the Th1 chemokines CXCL9 and CXCL10 enhance the tumor attack of effector T cells and increase PD-L1 blockade." (PMID 35531878, 2022). "This includes expression of type 1 interferons and T-cell-recruiting chemokines [C-C Motif Chemokine Ligand 5 (CCL5), C-X-C Motif Chemokine Ligand 10 (CXCL10)], leading to a higher level of tumor-infiltrating T-cells." (PMID 35327359, 2022). "When the Wnt signaling pathway is blocked, it can up-regulate the expression of chemokine CXCL10, improve T cells tumor infiltration in cancer models, and improve the efficacy of CAR-T cells in CRC treatment." (PMID 36238297, 2022). "Significant differences of serum CXCL10 levels were found between CESC patients at late tumor stage and CESC patients at early tumor stage (P < 0.01)." (PMID 36207693, 2022). "Recently, CXCL9 and CXCL10 were reported to be necessary for the trafficking of activated CD8+ T cells into tumor sites." (PMID 36284313, 2022). "The DEN/CCl4-treated Cxcl10−/− mice, in turn, displayed a significant enhancement of chemokines in tumor tissue in comparison to the surrounding tissue (Ccl5, Ccl2 and Ccl7)." (PMID 35897689, 2022). "CXCL10 activates anti-tumor immunity by inducing interferon gamma, and inhibits angiogenesis and prevents tumor growth." (PMID 35223493, 2022). "HCC tissue of the DEN/CCl4-treated Cxcl10−/− mice showed a slight reduction of proliferative Ki67+ tumor cells in comparison to tumorigenic WT tissue." (PMID 35897689, 2022). "The DEN/CCl4-treated Cxcl10−/− mice presented with a pro-inflammatory tumor microenvironment and an accumulation of anti-tumoral immune cells in the tissue." (PMID 35897689, 2022). "The presence of myeloid-cell-derived CXCL9 and CXCL10 in the tumor microenvironment can predict response to immunotherapy." (PMID 35626062, 2022). "CXCL10 levels were increased in both tumor cells and BAL fluids, which reflects factors originating from tumor and immune cells." (PMID 36612121, 2022). "Higher expression of CXCL10 and immune infiltrate in biopsies were previously associated with ICB monotherapy efficiency in different tumor types." (PMID 35794623, 2022). "Compared to WT counterparts, Cxcl10−/− mice showed a decreased tumor burden as evidenced by reduced total number and size of tumors." (PMID 35897689, 2022). "Multiple studies have shown that the STING signaling pathway affects tumor development through secretory proteins such as CXCL10, CCL5, and IFNs." (PMID 36496076, 2022). "One notable function of tumor associated eosinophils is their expression of chemokines, such as CXCX9, CXCL10 and CCL5, which further recruit CD8+ CTLs to the tumor sites." (PMID 36231078, 2022). "Studies revealed that siRNA blockade of STAT3 in glioma cells resulted in microglial stimulation as well as tumor growth blockade in murine models, with upsurges in IL-2, IL-4, IL-12, IL-15, and CXCL10 as well as upregulation of CD80 and CD86 on myeloid cells." (PMID 35419058, 2022).
tumor (continued). "For instance, DCs secrete CXCL9 and CXCL10 as chemoattractors for recruiting CXCR3+ T cells into the tumor microenvironment." (PMID 35347124, 2022). "BATF3- and CXCR1-DCs secrete CD141, which primes CD8+ T cells for anti-tumor activity and generates CXCL10 to recruit specific CD8+ T cells." (PMID 35205408, 2022). "The loss of PTPN2 results in an increase in tumor antigen presentation and T-cell trafficking due to enhanced expression of IFNγ-responsive genes, including MHC-I, Cxcl9, Cxcl10, Cxcl11, and Ccl5." (PMID 34385592, 2022). "Recent studies have revealed that ARID1A loss impairs the expression of IFN signaling components, especially Th1-type chemokines (CXCL9 and CXCL10), to compromise effector T-cell tumor trafficking and antitumor immunity." (PMID 36435834, 2022). "Blocking CXCL10/CXCR3 signaling results in a loss in M1 polarized macrophages, shifting macrophage populations to a tumor-promoting phenotype." (PMID 35493517, 2022). "Together, these data indicate that activated ACK1/EZH2 epigenetic signalling in tumour cells depletes the tumour microenvironment of the T-cell attractant CXCL10, maintaining T cells in an inactive state." (PMID 36376335, 2022). "We show here that miR-21-5p-mediated suppression of CXCL10, a potent endogenous inhibitor of angiogenesis, in HUVECs is in part responsible for tumor cell-induced angiogenesis and tumor growth in ESCC." (PMID 35346324, 2022). "In line with the previous results, qRT-PCR revealed an elevated expression of Il6, Infy, Il1ß and Il12 in the tumor tissue of the DEN/CCl4-treated Cxcl10−/− mice in comparison to the DEN/CCl4-treated WT mice." (PMID 35897689, 2022). "Consistently, knockdown of Cxcl10 in B16F0 cells impaired IFNα-MSC-induced CD8+ T cell infiltration into tumor." (PMID 35145233, 2022). "Accordingly, the data suggest that the slight reduction of tumor cell proliferation in Cxcl10−/− mice is a direct effect of the impairment of CXCR3–CXCL10 signaling." (PMID 35897689, 2022). "Recent studies have revealed that ARID1A loss impairs IFN signaling, especially Th1-type chemokine (CXCL9 and CXCL10) expression, to compromise effector T-cell tumor trafficking and antitumor immunity." (PMID 36435834, 2022). "Compared to those of tumor-bearing mice, the expression levels of stimulatory molecules, including CXCL10, IL-12, and IL-15, were significantly upregulated, while the expression level of IL-7 was downregulated." (PMID 36389684, 2022). "By specifically deleting SPATA2 and CYLD in human and mouse CRC cell lines, we showed that these two proteins inhibit STAT1 accumulation and activation and subsequently CXCL10 expression in tumor cells." (PMID 36531014, 2022). "The pro-inflammatory cytokine IFN-γ induces CXCR3 chemokines, e.g., CXCL-9 and CXCL-10, as part of the interferon-stimulated gene cluster that then attracts T cells into the tumor." (PMID 36611932, 2022). "Conversely, CXCL10 signalling via CXCR3 isoforms overexpressed upon transformed cells is implicated in the growth, invasion and metastasis of several tumour types." (PMID 35844527, 2022). "In lung and renal cell carcinoma models, intratumoral injection of CXCL9 or CXCL10 proteins, respectively, reduced neovascularization and delayed tumor growth by inducing tumor‐infiltrating CXCR3+ monocytes." (PMID 35702353, 2022). "Regarding the tumor-associated immune response, the DEN/CCl4-treated Cxcl10−/− mice display a massive infiltration of anti-tumoral immune cells such as CD8+ T cells and NK cells in comparison to their WT counterparts." (PMID 35897689, 2022). "Our results showed that tumor exo-NAC or exo-miR-155-5p decreases CXCL10 and CCL2 expression levels in macrophages." (PMID 35086548, 2022). "We observed increased migration of NK cells towards CHMP2A KO tumor cells that showed increased secretion of CXCL10 and CXCL12, chemokines involved in NK cell migration." (PMID 35393416, 2022).
tumor (continued). "Our findings suggest that miR-15a-5p is a tumor suppressor in ECD through the CXCL10-ERK-LIN28a-let7 axis, highlighting another layer of post-transcriptional regulation in this disease." (PMID 34785791, 2022). "CXCR3 and its corresponding ligands CXCL9 and CXCL10 are elevated in CRC and associated with tumor metastasis." (PMID 35791509, 2022). "CHMP2A-knockout (KO) tumor cells secrete more CXCL10 and CXCL12, increasing NK cell migration in vitro." (PMID 35393416, 2022). "Taken together, these data suggest that the enhancement of anti-tumoral immune cells in the DEN/CCl4-treated Cxcl10−/− mice shapes the tumor microenvironment in a tumor-suppressive manner." (PMID 35897689, 2022). "The presence of Batf3 DCs, CXCL9 and CXCL10 in the tumor microenvironment independently correlated with T cell infiltration." (PMID 35626062, 2022). "In this study, serum CXCL10 levels after treatment decreased significantly, and serum CXCL10 concentrations at baseline were higher in more advanced tumor stages." (PMID 36207693, 2022). "The KDM4C-specific epigenetic inhibitor SD70 can reshape the tumor state, activate the expression of CXCL10, and enhance the recruitment and activation of CD8+ T cells, ultimately making tumors more responsive to RT and immunotherapy." (PMID 35121645, 2022). "IP-10 (CXCL10) was higher in BCW0 tumor tissue compared to BCW12 and demonstrated that trend compared to BCW12OFS." (PMID 35681702, 2022). "Fifteen distinct clusters were identified and five clusters (M_C1_PLTP, M_C3_CCL20, M_C4_CXCL10, M_C5_NBEAL1, and M_C12_CD207) were abundant in tumor." (PMID 35102420, 2022). "It regulates the levels of STING, CXCL10, and therefore inflammatory infiltrates of the tumor microenvironment, in particular CD8+ T lymphocytes, which in turn correlate with survival." (PMID 36499710, 2022). "Together, our results imply that Type17 cells secrete CCL20 to mediate DC migration to the tumor, resulting in increased secretion of CXCL10 by DCs in the tumor." (PMID 35459193, 2022). "There is a strong correlation between insufficient expression of CXCL10 and poor prognosis at tumor sites in various human cancers." (PMID 35710862, 2022). "Recent discoveries reveal several mechanisms, such as epigenetic silencing of CCL5, CXCL9, and CXCL10 in different tumor entities or post-translational cleavage of those same chemokines by enzymes such as dipeptidylpeptidase 4 or matrix metalloprotease-9." (PMID 36366354, 2022). "C-X-C chemokine ligand-10 (CXCL10) is a protein in the chemokine group that is a surface protein involved in inflammation, tumor metastasis, angiogenesis and wound healing." (PMID 35269967, 2022). "We found that IFNα-MSCs induced enriched CXCL10 expression in tumor cells which is responsible for the chemotaxis of CD8+ T cells to the tumor site." (PMID 35145233, 2022). "Among many other cytokines and chemokines, CXCL10 was tested as an immune stimulant in the genomes of oncolytic viruses, to enhance the anti-tumor activity in several cancer studies." (PMID 36366543, 2022). "The tumor cells were incubated with L. paracasei sh2020 for 4 h, 8 h, 16 h, 24 h, and 36 h, respectively, secretion of CXCL10 protein was measured using ELISA assays." (PMID 35259052, 2022). "The CTSB on tumor cells surface can remove the autoreactive lymphocytes and degrade these cytotoxic effector molecules (such as IgG and chemokines CXCR3, CXCL9, CXCL10) synthesized from tumor-suppressive infiltrating immune cells." (PMID 35277559, 2022). "By contrast, TAMs can secrete soluble factors including growth factors, cytokines, and chemokines such as transforming growth factor [TGF]-β, vascular endothelial growth factor, M-CSF, IL-10, and CXCL10 to induce tumor progression and metastasis." (PMID 35960749, 2022). "Our results show that increased CXCL10 levels during early EGFR-TKI treatment stimulate oncogenic signaling of persistent tumor cells to contribute to EGFR-TKI resistance via autocrine and paracrine pathways." (PMID 36612121, 2022).
tumor (continued). "To study the functional roles of these T cell-recruiting chemokines, we used neutralizing antibodies to antagonize the expression of CCL5, CXCL9, and CXCL10 in JQ-1-treated tumor-bearing mice." (PMID 35292660, 2022). "Despite induction of immunogenic cell death process, chemotherapy is unable to promote CXCL10 production at the tumor site and immune recruitment." (PMID 35529902, 2022). "cDC1 are the major source of CD8+ T cell chemoattractants CXCL9 and CXCL10; these chemokines drive T cell recruitment and anti-tumor immunity as well as suppress angiogenesis by secretion of anti-angiogenic factor such as IL-12 and IL-18." (PMID 35759090, 2022). "Overall, our findings are consistent with miR-15a-5p’s role as a tumor suppressor that acts by downregulating CXCL10 and LIN28a expression through inhibition of the MAPK-ERK pathway." (PMID 34785791, 2022). "We demonstrated that high CXCL10/STAT2 expression was associated with activation of T-cell pathways, increased tumor infiltration of Th1 and CD8+ T cells, and better patient outcome." (PMID 35207629, 2022). "Liver tissue of the DEN/CCl4-treated Cxcl10−/− mice displayed the same level of Lag3 in the surrounding and tumor tissue." (PMID 35897689, 2022). "Taken together, these data suggest that the enhancement of tumor-fighting immune cells in the DEN/CCl4-treated Cxcl10−/− mice shapes the tumor microenvironment in a tumor-diminishing manner, which fostering immune surveillance and tumor rejection." (PMID 35897689, 2022). "CXCR3, which is expressed on Th1, macrophage and NK cells, and its ligands (CXCL9, CXCL10) is an important chemokine axis in tumor suppression via interferon-induced cell-mediated immunity and inhibition of angiogenesis." (PMID 36132332, 2022). "Related to this, CCL2 is a primary recruiter of tumour monocyte subsets and CXCL10 is known to be a monocyte recruitment factor." (PMID 35226704, 2022). "Our bulk RNA sequencing data on DRGs from MC38 tumor-bearing mice also revealed a significant increase in the expression of CXCL10." (PMID 35962398, 2022). "A mouse model revealed the importance of eosinophils in improving the infiltration of CD8+ T cells into the tumor by CCL5, CXCL9 and CXCL10 production, thus referring to their active participation in tumor rejection." (PMID 35565423, 2022). "In summary, deletion of Cxcl10 in tumor-bearing mice leads to an overall reduction of chemokines but to a specific accumulation at the tumor site." (PMID 35897689, 2022). "High level of CXCL10 in tumor tissues attracts CXCR3+ Th1 and CD8+ T cells to inflamed tumor sites and stimulates T-cell polarization into effector T cells to promote killing of cancer cells." (PMID 35207629, 2022). "In the literature, it is described that the CXCR3/CXCL9/CXCL10 signaling axis modulates the proliferation, migration and survival of tumor and endothelial cells." (PMID 35897689, 2022). "Among these chemokines, the tumor cell-derived chemokines CXCL9 and CXCL10 are critical in attracting CD8+ T lymphocytes to tumor tissues." (PMID 36284313, 2022). "While CXCL1 and CXCL10 levels significantly decreased after tumor resection, postoperative CXCL13 levels were significantly higher compared to preoperative values." (PMID 36077611, 2022). "We demonstrated overexpression of CXCL9 in mDC_LAMP3 and Macro-2 cells, and overexpression of CXCL10 in proliferating macrophages (Pro Macro) and Macro-2 cells in the tumor." (PMID 36180422, 2022). "Among them, Cxcl9, Cxcl10, and Cxcl11 are most related to the recruitment of CD8+ T cells, as CXCR3, the cognate receptor for CXCL9 and CXCL10, is highly expressed in tumor infiltrated CD8+ T cells." (PMID 35145233, 2022). "Overexpression of CXCR3-A and its ligand CXCL10 mediate p38/MAPK, ERK1/2, JNK signaling pathway to cause intracellular calcium influx and promote tumor invasion, migration and metastasis." (PMID 35083488, 2022).
tumor (continued). "Through activation of MC via TLR4, MC secrete CXCl10, which recruits tumor-specific T cells for effective antitumor responses." (PMID 35326379, 2022). "These IFNα-MSCs promoted tumor cells to produce CXCL10, which in turn potentiates the infiltration of CD8+ T cells in the tumor site." (PMID 35145233, 2022). "This association was further validated in the TCGA-BLCA and Japanese UTUC cohorts, where the basal subtype showed significantly enhanced CXCL10 expression and a greater number of tumor-infiltrating CD8+ T cells and macrophages." (PMID 36451860, 2022). "We suggest that CXCL10 differs from other chemokines by its ability to restrain tumor growth and enhance antitumor immunity." (PMID 36230645, 2022). "CXCL9 and CXCL10 produced by myeloid cells in CRC liver metastases induce tumor-infiltrating lymphocytes to invade the margins." (PMID 35935996, 2022). "For example, systemically administered bacterial EVs accumulated in tumour tissue and triggered the release of antitumour cytokines CXCL10 and interferon-γ, which led to the suppression of tumour growth." (PMID 36290464, 2022). "Some literature suggests that CXCL11 and CXCL10 can promote the proliferation and metastasis of tumor cells." (PMID 35432485, 2022). "Cleaved caspase 3 staining demonstrated that deletion of Cxcl10 leads to a minor enhancement of tumor cell death in the DEN/CCl4-treated Cxcl10−/− mice in comparison to the DEN/CCl4-treated WT mice." (PMID 35897689, 2022). "In terms of liver metastasis, the interferon-α response gene set was enriched in a tumor burden of ≥1 cm3, and CXCL10, CXCL11 and SAMD 9 were highly expressed in the exosomal RNA which was validated using GSEA." (PMID 36230645, 2022). "In this context, CXCL10 was shown to contribute to the therapeutic success of this treatment by promoting the recruitment of CXCR3+CD8+ T cells at the tumor site." (PMID 36429101, 2022). "The high expression of TGF-β, VEGFA, and CXCL10 and the low expression of TNF-α indicated the tumor-supporting effect of GAMs in high risk score group." (PMID 36159780, 2022). "CXCL10 originates from both immune and tumor cells, and exogenous CXCL10 stimulates persistent tumor cells to produce endogenous CXCXL10." (PMID 36612121, 2022). "In HNSCC HPV+, the values of KDM5B are inversely related to those of STING, to CXCL10 (one of the interferon-induced chemokines that promotes inflammatory infiltrate in the tumor microenvironment), and to the amount of CD8+ infiltrate." (PMID 36499710, 2022). "AIM2-deficient DC promoted tumor antigen–specific CD8+ T cell infiltration into the tumor via CXCL10." (PMID 35739593, 2022). "Blockade with an anti-PD-1 antibody enhanced proliferation of T cells and thereby increased expression of IFN-γ in the tumor microenvironment which in turn increased production of CXCL10 (Interferon gamma-induced protein 10)." (PMID 35626062, 2022). "CXCL9 and CXCL10 can effectively inhibit angiogenesis, enhance apoptosis and immune infiltration of tumor cells, and enhance antitumor immunity in platinum-based chemotherapy drug treatment." (PMID 36590751, 2022). "The association of CXCL10 and CXCL11 with diverse human conditions like immune dysfunction and tumour progression has been documented." (PMID 33960101, 2022). "A protein array on a lysate of tumors treated with MTX alone displayed a more than 1.5 fold increase of CCL17, CXCL11, CD160 and CXCL10, as compared to control tumor lysate." (PMID 36397148, 2022). "With regard to tumor vascularization, the DEN/CCl4-treated Cxcl10−/− mice displayed a reduced tumor-associated angiogenesis compared to WT counterparts." (PMID 35897689, 2022). "Cytotoxic CD8+ T cells secrete IFN-γ, which suppresses tumor angiogenesis by inhibiting the proliferation of ECs and upregulating cytokine-encoding genes (e.g., CXCL9, CXCL10, and CXCL11)." (PMID 35759090, 2022).